FOXA3 (forkhead box A3)
Diseases named in the same sentence as FOXA3 in open-access papers (continued):
Sharing a sentence is not in itself a finding about the gene and the disease.
colorectal cancer (2 papers, 2021 to 2024). A primary or metastatic malignant neoplasm that affects the colon or rectum. "In summary, combined expression of HHEX and Foxa3 exhibited a suppressive effect on tumorigenesis in the colitis-associated colorectal cancer model." (PMID 34595169, 2021). "However, FOXA3 was demonstrated to repress stemness of colorectal cancer cells via targeting MACC1, whose gene expression is enriched in neural cells during early embryogenesis." (PMID 34595169, 2021). "Among the regulons driving classical states were those driven by TBX10, PDX1, FOXA3 and CDX2, which is a known prognostic marker in gastrointestinal cancers, especially colorectal cancer, and has been described as a lineage survival oncogene." (PMID 39417106, 2024).
esophageal cancer (2 papers, 2020 to 2023). A primary or metastatic malignant neoplasm involving the esophagus. "FOXA3 upregulation is identified in the esophageal cancer samples, and its level is positive correlated with invasion and metastasis in EC." (PMID 37876483, 2023). "FoxA3 was also up-regulated and promoted metastasis in esophageal cancer cells through the regulations of FoxA1 and FoxA2 expressions." (PMID 32151057, 2020). "FOXA3 was predicted to be a similar gene to HOXC10 in esophageal cancer." (PMID 37876483, 2023). "In addition, patients with esophageal cancer were also predicted to unfavorable survival with high levels of FOXA3 (HR = 2.11[1.1–4.04], P = 0.021)." (PMID 37876483, 2023). "FoxA1, FoxA2 and FoxA3 play synergistic roles in metastasis of esophageal cancer." (PMID 32151057, 2020). "Based on the STRING and GEIPA databases, FOXA3 and HOXC10 were co-expressed and their expression was positively correlated in esophageal cancer (R = 0.46, p = 9.1e-11)." (PMID 37876483, 2023). "Based on the bioinformatics analysis, FOXA3 is a similar gene to HOXC10, and their expression is positively correlated in esophageal cancer." (PMID 37876483, 2023).
liver disease (2 papers, 2017 to 2026). "So far, it remains unknown whether hepatic FOXA3 is essential for regulating lipid metabolism or metabolic dysfunction-associated liver disease (MASLD)." (PMID 41683889, 2026). "We tried to investigate factors involved in biliary atresia, especially forkhead box A3 (Foxa3), which might exert a role in the treatment of liver disease." (PMID 28358366, 2017).
liver fibrosis (2 papers, 2017). "We found that Foxa3 expressing adenovirus transduction significantly weakened liver fibrosis induced by BDL." (PMID 28358366, 2017). "Further investigation by bile duct ligation (BDL)-induced biliary atresia model indicated that ectopic expression of Foxa3 was significantly attenuated liver fibrosis." (PMID 28358366, 2017). "Our data suggested a protection role for Foxa3 during the progression of liver fibrosis in biliary atresia, and thereby supported increasing Foxa3 as a targeted treatment strategy." (PMID 28358366, 2017).
mucinous adenocarcinoma (2 papers, 2022 to 2023). An invasive adenocarcinoma composed of malignant glandular cells which contain intracytoplasmic mucin. "A gene signature of invasive mucinous adenocarcinoma of the lung, which includes transcription factors (FOXA3, SPDEF, and HNF4A) and mucin proteins (MUC5AC, MUC5B, and MUC3) has been identified." (PMID 36860703, 2022). "Additionally, markers of invasive mucinous adenocarcinoma (MUC5AC, MUC5B, SPDEF, FOXA3) were highly expressed in organoids, retaining the histological characteristics of the patient’s original tumor." (PMID 37508518, 2023).
prostate carcinoma (2 papers, 2022 to 2024). A carcinoma that arises from epithelial cells of the prostate gland. "Almost all of the FOX genes were differentially expressed in prostate cancer, prostate carcinoma, and metastatic prostate cancer, except FOXA3, FOXB2, FOXC2, FOXI2, FOXI3, FOXP4, and FOXR1." (PMID 36292640, 2022).
allergic asthma (1 paper, 2026). A asthma with a basis in a pathological type I hypersensitivity reaction. "Within the respiratory system, FOXA1, FOXA2, and FOXA3 have emerged as modulators of pulmonary inflammation, with important implications for the pathogenesis of allergic asthma." (PMID 41868652, 2026).
biliary atresia (1 paper, 2017). A rare, biliary tract disease characterized by progressive obliterative cholangiopathy of the intra- and extrahepatic bile ducts, occurring in the embryonic/ perinatal period, leading to severe and persistent neonatal jaundice and acholic stool. "Low expression of Foxa3 was associated with poor overall survival of biliary atresia patients (log-rank=8.379, P=0.0038)." (PMID 28358366, 2017). "More importantly, we found that lower expression of Foxa3 predicted a poorer overall survival of biliary atresia patients." (PMID 28358366, 2017). "Then, we employed a rat disease model by bile duct ligation (BDL) and adenovirus transduction to address the function of Foxa3 in biliary atresia." (PMID 28358366, 2017). "Our data showed that Foxa3 was notably decreased in liver samples from biliary atresia patients as evaluated by qRT-PCR, western blotting and immunohistochemistry staining." (PMID 28358366, 2017). "Here, among the downregulated genes identified, Foxa3 was confirmed to be downexpressed in biliary atresia livers by western blot and immunohistochemical staining." (PMID 28358366, 2017). "To further explore the functions of Foxa3 on biliary atresia in vivo, we established a rat biliary atresia model by BDL." (PMID 28358366, 2017). "In summary, we reported the expression profile of biliary atresia, and indicated the clinical value of Foxa3 in patients with biliary atresia although there is still long way to go before it can be applied to the clinic." (PMID 28358366, 2017). "We showed that Foxa3 expression was notably decreased in liver samples from biliary atresia patients." (PMID 28358366, 2017). "Our data suggested that Foxa3 was a potential prognosis factor for biliary atresia and it may exert antifibrotic effects during the pathogenesis of this disease." (PMID 28358366, 2017). "Furthermore, comparing with control livers, a significant increase in protein level of CTGF and a notable decrease in protein level of Foxa3 were observed in biliary atresia livers as measured by western blot and immunohistochemistry staining." (PMID 28358366, 2017). "Based on our current findings, Foxa3 could be a promising target gene for biliary atresia therapy owing to its downregulation in biliary atresia livers." (PMID 28358366, 2017).
craniosynostosis (1 paper, 2026). Craniosynostosis is defined as the premature fusion of one or more cranial sutures leading to secondary distortion of skull shape resulting in skull deformities with a variable presentation. "Network analysis nominated Foxa3 as a candidate regulator in SuSC subsets; siRNA knockdown of Foxa3 reduced ex vivo mineralization in the craniosynostosis background." (PMID 42071254, 2026).
Fanconi-Bickel syndrome (1 paper, 2016). "Since a reduction in GLUT2 expression has been related to reduced hepatic glucose efflux in several conditions, such as the Fanconi-Bickel syndrome and the Foxa3-/- mice, this result points out the hepatic territory as responsible for the beneficial effects of resveratrol." (PMID 27366200, 2016).
glioblastoma (1 paper, 2021). The most malignant astrocytic tumor (WHO grade IV). "We examined the effect of HHEX and another non-neural factor, Foxa3, on the neural stemness of glioblastoma cell U118MG and NSC NE-4C." (PMID 34595169, 2021).
injury (1 paper, 2025). Damage inflicted on the body as the direct or indirect result of an external force, with or without disruption of structural continuity. "Forkhead box protein A3 (FOXA3), a transcription factor, has been predominantly expressed in hepatocytes and cholangiocytes during the regeneration after PH and CCl4-induced liver injury in mice." (PMID 40304568, 2025).
lung adenocarcinoma (1 paper, 2024). A carcinoma that arises from the lung and is characterized by the presence of malignant glandular epithelial cells. "Altogether, our findings shed light onto unique cholesterol metabolism and FOXA3 contribution to lung adenocarcinoma metastasis." (PMID 38805565, 2024). "Conversely, FOXA3 knockdown or knockout blocked cholesterol biosynthesis and lung adenocarcinoma metastasis in mice." (PMID 38805565, 2024). "In addition, the potent FOXA3 inhibitor magnolol suppressed metastatic gene programs in lung adenocarcinoma patient-derived organoids (PDOs)." (PMID 38805565, 2024).
lung mucinous adenocarcinoma (1 paper, 2023). "Moreover, HNF-4α is reported as part of the signature genes of invasive lung mucinous adenocarcinoma, together with FOXA3, SPDEF and mucins, such as MUC5AC, MUC5B, and MUC3." (PMID 36674438, 2023).
magnesium deficiency (1 paper, 2022). A nutritional condition produced by a deficiency of magnesium in the diet, characterized by anorexia, nausea, vomiting, lethargy, and weakness. "An effect of FOXA3 cannot explain the association of the polymorphisms with a magnesium deficiency; however, it is known that magnesium deficiency produces an increase in LDL levels." (PMID 35625529, 2022).
papilloma (1 paper, 2017). A benign epithelial neoplasm that projects above the surrounding epithelial surface and consists of villous or arborescent outgrowths of fibrovascular stroma. "Although both transgenic mouse models developed mucinous lung tumors, induction of SPDEF along with KRASG12D produced malignant mucinous lung tumors (tubulopapillary‐like carcinoma), while induction of FOXA3 along with KRASG12D produced benign mucinous lung tumors (e.g., papilloma)." (PMID 28255028, 2017).
steatosis (1 paper, 2022). Increased lipid within the cytoplasm of cells. "A bridge between ERS and steatosis is represented by Forkhead box A3 (FOXA3), a member of FOXA family." (PMID 35630058, 2022).
tumor (15 papers, 2017 to 2025). "Taken together, in CCA, FoxA1 is down-regulated and has tumor suppressive roles, whereas FoxA3 is up-regulated and has oncogenic roles." (PMID 32151057, 2020). "In our work, we identified the increase in FOXA3 levels in ESCC tumor samples and cells." (PMID 37876483, 2023). "FOXA3-KO mice have normal lifespan without a tumor-prone phenotype, and FOXA3 mutations have not been reported in human cancer." (PMID 35703180, 2022). "Xenograft tumor formation by antibiotic selected cells might compromise the repression effect of Foxa3 or HHEX on tumorigenicity." (PMID 34595169, 2021). "Moreover, FOXA1, FOXA2, and FOXA3 were also grouped together with the tumor/invasion suppressor genes EPHB2 and EPHB3, and with the intestine-specific differentiation genes CDX1 and CDX2 (cluster 2)." (PMID 29155818, 2017). "In addition, among the enriched TFs in NN-HF, we further identified NFκB-P65, FOXA3, FOXD3, SIX1, CDX2, and MEF2C which have been found to impact tumor progression." (PMID 38720110, 2024). "Two significant pathways, hsa04080, Neuroactive ligand-receptor interaction, and hsa04950, Maturity onset diabetes of the young (MODoY; with transcription factors FOXA3, NKX6-1, MAFA, PAX6, PDX1), were identified for the genes expressed more highly in the high-CCNE1 tumours." (PMID 38612869, 2024). "Moreover, FOXA3 mRNA and protein were found to be upregulated in ESCC tumour samples relative to NTs." (PMID 37876483, 2023). "Therefore, mice in the control group developed heavier tumor burdens than the mice with expression of HHEX and Foxa3, or HHEX and Foxa3 expression in colon generated a suppressive effect on tumorigenesis." (PMID 34595169, 2021). "Further, we employed SCENIC to predict transcription patterns of tumor cells, finding a series of key TFs of HCC tumorigenesis, such as TFs in regulation of cell dedifferentiation (SPI1, HMGB3, and YBX1) and in abnormal bile acid metabolism (NR1H4, NR1I3, FOXA3 and DDIT3)." (PMID 37985711, 2023). "However, the sorted cells with Foxa3 expression did not form tumor, an effect somewhat different from injection of antibiotic selected cells." (PMID 34595169, 2021). "However, Foxa3 could be detected in xenograft tumors derived from both cell mixtures, suggesting that Foxa3-expressing cells did not contribute to tumor formation." (PMID 34595169, 2021).
cancer (14 papers, 2015 to 2025). A tumor composed of atypical neoplastic, often pleomorphic cells that invade other tissues. "We also show that combined expression of HHEX and FOXA3 suppresses tumorigenesis effectively in the AOM/DSS model of colitis-associated cancer." (PMID 34595169, 2021). "Enforced HHEX or Foxa3 expression led to repression of cell migration and invasion, consistent with the repression effect of cancer-promoting factors." (PMID 34595169, 2021). "A previous animal study has suggested that the induction of the signature genes FOXA3 or SPDEF, which are enriched in mucin-producing cancers, along with a KRAS mutation in the lung epithelium, is sufficient to develop mucinous lung tumors in transgenic mice." (PMID 34174841, 2021). "Enforced expression of HHEX or Foxa3 caused significant morphological change in U118MG cells and changes in expression of a series of cancer-promoting factors." (PMID 34595169, 2021). "High expression of FoxA3 in cancer tissues (61%) was significantly related to high metastasis status." (PMID 32151057, 2020). "FoxA3 was highly detected in the nucleus and cytoplasm of the cancer cells." (PMID 32151057, 2020). "Therefore, this confirmed that FoxA3 has oncogenic functions via the inductions of proliferation and invasion of the cancer cells lead to intrahepatic CCA progression with aggressive clinical outcomes such as high metastasis." (PMID 32151057, 2020). "The activities of SREBF1 and FOXA1 were higher in the primary cancer samples, while the activities of FOXC1 and TP73 were higher in normal samples, and the activities of transcription factors such as FOXA3 were higher in the CRPC samples." (PMID 39988626, 2025). "Similarly to GAL3ST1, PRAME and FOXA3 genes were also silent under CTCF occupancy, but were activated upon CTCF and BORIS co-binding in both cancer and germ cells." (PMID 26268681, 2015). "Besides, the frequency of TPR|FOXA3 and ABCA 7|DOCK2 were larger than 0.1 in more than 10 cancers." (PMID 36139377, 2022). "Next, we tested whether HHEX and Foxa3 could repress tumorigenesis in the Azoxymethane/Dextran Sodium Sulfate (AOM/DSS) mouse model of inflammatory colorectal cancer, a well-established and frequently used cancer model." (PMID 34595169, 2021). "Moreover, it has been not reported whether HHEX or Foxa3 or their combination can repress tumorigenesis in colon using a mouse cancer model." (PMID 34595169, 2021).
infection (5 papers, 2014 to 2022). The state of being infected such as from the introduction of a foreign agent such as serum, vaccine, antigenic substance or organism. "In order to quantify mucus metaplasia in whole lungs of control and Pou2f3-/- animals, we analyzed gene expression of goblet cell markers, Foxa3, Agr2, Muc5ac, and Muc5b, 51 days post infection." (PMID 36073526, 2022). "At MOI 1 or 5 for HRV-A16, we found that gene expression of SPDEF, FOXA3, and AGR2 were significantly increased in ALI-PBEC at 48 h post-infection." (PMID 32637364, 2020). "Thus, in this study, we sought to examine whether induced hepatocyte-like (iHep) cells, which were directly induced from mouse dermal fibroblasts by infection with a retrovirus expressing Hnf4α and Foxa3, possess the potential for lipid metabolism, similar to hepatocytes." (PMID 25364750, 2014).
metabolic disorders (2 papers, 2023 to 2024). "Mechanistically, hepatic FOXA3 induces lipolysis and thermogenesis and prevents Western diet–induced metabolic disorders via TGR5." (PMID 38447926, 2024).
adenocarcinoma (1 paper, 2009). A common cancer characterized by the presence of malignant glandular cells. "RT-PCR confirmed that amphiregulin (Areg), epiregulin (Ereg), fetuin beta (Fetub), claudin 2 (Cldn2), hepatic nuclear factor 4, alpha (Hnf4α), glutathione S-transferase, alpha 4 (Gsta4) and forkhead box A3 (Foxa3) were up-regulated in adenocarcinoma." (PMID 19812696, 2009).
reproductive diseases (1 paper, 2023). "Among the DEGs identified in F1 testes, Foxa3 and RNAse L are implicated in reproductive diseases." (PMID 36982971, 2023).
FOXA3 also shares sentences with these, for which no sentence is quoted: gastric cancer (2 papers); pancreatic cancer (2); ciliopathies (1); colitis (1); colon adenocarcinoma (1); endometriosis (1); esophageal squamous cell carcinoma (1); Fanconi anemia (1); gastroesophageal junction adenocarcinoma (1); genitourinary cancers (1); hearing loss (1); hyperlipidemia (1); intrahepatic cholangiocarcinoma (1); maturity-onset diabetes (1); metabolic dysfunction-associated steatohepatitis (1); metastatic prostate carcinoma (1); pancreatic adenocarcinoma (1); periodontitis (1); Pneumocystis infection (1); primary sclerosing cholangitis (1); prostatic neoplasms (1); rectum adenocarcinoma (1); stomach adenocarcinoma (1); type 1 diabetes mellitus (1).